NFKBIA (NFKB inhibitor alpha)
Diseases named in the same sentence as NFKBIA in open-access papers (continued):
Sharing a sentence is not in itself a finding about the gene and the disease.
endometriosis (7 papers, 2016 to 2022). The growth of functional endometrial tissue in anatomic sites outside the uterine body. "High serum IL-6 concentrations in endometriosis patients are probably related to the reduction in conserved helix-loop-helix ubiquitous kinase (CHUK) protein as well as NF-κB inhibitor alpha (NFKBIA) mRNA and the p-NFKBIA/NFKBIA protein ratio." (PMID 32145751, 2020). "While there is no direct evidence for a role of endometrial NFKBIA in fertility, NFKBIA expression and phosphorylation of IκBα are reduced in the endometrium of endometriosis patients with reduced fertility." (PMID 35358206, 2022).
endometritis (7 papers, 2017 to 2024). An acute or chronic, usually bacterial infectious process affecting the endometrium. "A total of 14 predicted upstream regulators were identified only in healthy cows (P < 0.05), while five unique predicted upstream regulators were identified only in cows after uterine infection, including the inhibition of ISG15 and AIRE, and activation of DUSP1, NFKBIA, and PF4 (P < 0.05)." (PMID 35358206, 2022). "Nuclear factor kappa B inhibitor alpha (NFKBIA), which encodes for IκBα, is involved in both iNOS and TLR signaling pathways and was identified as a discordant, activated upstream regulator of pregnancy regulated genes in cows following uterine infection and not in healthy cows." (PMID 35358206, 2022).
Hepatitis (7 papers, 2014 to 2025). Inflammation of the liver.
atopic dermatitis (6 papers, 2017 to 2024). "The top differentially expressed genes (DEG) between AGS subjects and controls included transcription factors regulating immune gene expression, such as the NFκB pathway (NFKBIA, NFKB2, REL), antigen presentation molecules, type 2/allergic immune responses, itch, and allergic dermatitis." (PMID 33804792, 2021).
neuroblastoma (6 papers, 2008 to 2024). Neuroblastoma (NB) is the most common solid, extracranial childhood tumor. "In line with this, our study demonstrated, through qRT-PCR and WB, that SHPRH-146aa overexpression significantly increased NFKBIA expression in neuroblastoma cells." (PMID 38282862, 2024).
osteoporosis (6 papers, 2016 to 2025). A condition of reduced bone mass, with decreased cortical thickness and a decrease in the number and size of the trabeculae of cancellous bone (but normal chemical composition), resulting in increased fracture incidence. "Results revealed significant differential expressions of DDIT4, FOXO1, NFKBIA, PGK1, and STAT3 in the osteoporosis model." (PMID 41282482, 2025). "Differential expression analysis in osteoporosis and sarcopenia datasets revealed that seven biomarkers—BCL6, DDIT4, FOXO1, IRS1, NFKBIA, PGK1, and STAT3—were differentially expressed in the independent osteoporosis dataset GSE84500." (PMID 41282482, 2025). "Furthermore, bioinformatics analysis revealed that RELA, NFKBIA, and IKBKB, which all belong to the NF-κB family, were hub genes shared between ICA-targeted genes and osteoporosis." (PMID 34803690, 2021).
schizophrenia (6 papers, 2018 to 2022). A major psychotic disorder characterized by abnormalities in the perception or expression of reality. "In order to further explore the diagnostic value of the four hub genes (NFKBIA, CDKN1A, BTG2, and GADD45B) for schizophrenia, this experiment used ROC curves for evaluation." (PMID 35741729, 2022). "Based on bioinformatics methods, this is the first study that found four hub genes closely related to schizophrenia (NFKBIA, CDKN1A, BTG2, and GADD45B)." (PMID 35741729, 2022). "In conclusion, NFKBIA, CDKN1A, BTG2, GADD45B, and the joint indicators of four hub genes have great potential as biomarkers and therapeutic targets for the diagnosis of schizophrenia." (PMID 35741729, 2022).
brain tumors (5 papers, 2005 to 2024). "MLPA analysis did not reveal any differences between DK-MG lines, other than EGFRvIII, with both lines having normal number of wild-type EGFR copies, hemizygous PTEN and NFkBIA, and CDKN2A deleted; all mutations reminiscent of brain tumors." (PMID 27004406, 2016). "However, alterations of NFKBIA have not been examined in relation to expression subtype and the mRNA expression of NFKBIA is actually elevated in MES tumors (GlioVis data portal for visualization and analysis of brain tumor expression datasets)." (PMID 30200302, 2018).
diabetic nephropathy (5 papers, 2014 to 2025). "NFKBIA regulates the activity of NFκB, which plays a role in processes such as the accumulation of advanced glycation end products and activation of the renin–angiotensin system pathways, protein kinase C, and oxidative stress in diabetic nephropathy." (PMID 38674089, 2024).
diffuse large B-cell lymphoma (5 papers, 2020 to 2025). "BAX and NFKBIA were implicated in susceptibility to CG-806 in a whole-genome CRISPR-Cas9 library screen (in a diffuse large B-cell lymphoma cell line)." (PMID 35296646, 2022).
HIV-1 infection (5 papers, 2019 to 2025). The type species of lentivirus and the etiologic agent of acquired immunodeficiency syndrome (AIDS). "In the gene-pathway connections, multiple molecules and kinases for NF-κB signaling (e.g., IKBKB, JUN, FOS, MAP2K2, NFKBIA, TLR4) connected the HIV-1 infection and other inflammatory or anti-viral pathways." (PMID 39283947, 2024).
multiple sclerosis (5 papers, 2011 to 2022). A progressive autoimmune disorder affecting the central nervous system resulting in demyelination. "We found that one patient had a single copy gain of the NFKBIA gene, previously shown to be related to Crohn's diseases and multiple sclerosis." (PMID 21851588, 2011).
myocardial infarction (5 papers, 2020 to 2023). Gross necrosis of the myocardium, as a result of interruption of the blood supply to the area, as in coronary thrombosis. "Silencing ATP2B1-AS1 protects mice from myocardial infarction by blocking the NFKBIA mediated NF-κB signaling pathway." (PMID 36998473, 2023). "Study finds that blocking NFKBIA-mediated NF-κB signalling pathway can protect against myocardial infarction in mice." (PMID 34286341, 2021).
oral cancer (5 papers, 2012 to 2022). "The purpose of this study was to evaluate the associations of polymorphisms in NFKB1 and NFKBIA with oral cancer susceptibility, and further explore their potential mechanism in vitro." (PMID 29635862, 2018). "First, the polymorphisms of NFKB1 and NFKBIA were genotyped through iPLEX Sequenom MassARRAY platform in a case–control study with 425 oral cancer patients and 485 healthy controls." (PMID 29635862, 2018). "The combination of polymorphism of nuclear factor kappa B1 (NFKB1) -94 ATTG, NFKBIA -826 T,-881 G alleles and environmental carcinogen were associated with increasing risk of betel-quid related oral cancer." (PMID 28404909, 2017). "The synergistic effect of environmental factors (betel quid and smoking) and NFKBIA −881 and −826 polymorphisms on the risk of oral cancer was also demonstrated adequately." (PMID 22509384, 2012). "Patients with oral cancer carrying at least one T allele of NFKBIA −519 are at higher risk of developing distal metastasis, compared with patients carrying C/C homozygotes." (PMID 22509384, 2012). "The combination of NFKB1 or NFKBIA gene polymorphisms and environmental carcinogens appears related to an increased risk of oral cancer." (PMID 22509384, 2012). "The current study investigated relationships between SNPs in the promoter regions of the NFKB1 and NFKBIA genes and the risk of oral cancer." (PMID 22509384, 2012). "A combination of NFKB1or NFKBIA gene polymorphisms and environmental carcinogenesis may be related to an increased risk of oral cancer." (PMID 36518124, 2022). "Therefore, this study aims to examine the association of NFKB1 and NFKBIA genes polymorphisms with the susceptibility to oral cancer in southeast China, and further explore their biological mechanism on oral cancer in vitro." (PMID 29635862, 2018). "Moreover, we found that NFKB1 or NFKBIA gene polymorphisms seem to be related to susceptibility to develop oral cancer linked to betel nut and tobacco consumption." (PMID 22509384, 2012). "Finally, patients with oral cancer who had at least one −519 T allele of the NFKBIA gene were at higher risk for developing distant metastasis (P<.05), compared with those patients CC homozygotes." (PMID 22509384, 2012). "Among betel nut consumers in the cohort, tobacco smoking elevated oral cancer risk significantly in participants polymorphic for NFKB1 in the −94 locus or NFKBIA in three loci (−519, −826, and −881), compared with people with the WT gene who did not smoke tobacco." (PMID 22509384, 2012). "Distribution frequencies for NFKB and NFKBIA genotypes in 520 controls and 462 oral cancer patients." (PMID 22509384, 2012). "Adjusted odds ratio (AOR) and 95% CI for oral cancer associated with NFKB and NFKBIA genotypic frequencies and cigarette smoking among 444 betel nut consumers." (PMID 22509384, 2012). "Adjusted odds ratio (AOR) and 95% CI for oral cancer associated with NFKB and NFKBIA genotypic frequencies and betel nut chewing among 598 smokers." (PMID 22509384, 2012). "Genetic polymorphisms of NFKB1 and NFKBIA were analyzed by a real-time polymerase chain reaction (real-time PCR) for 462 patients with oral cancer and 520 non-cancer controls." (PMID 22509384, 2012). "In conclusion, our results suggest that NFKB1 gene polymorphisms might be correlated with oral cancer susceptibility, and the combined effect of NFKB1 or NFKBIA gene polymorphisms with environmental carcinogens increases risk of oral cancer development significantly." (PMID 22509384, 2012). "Moreover, people who were either polymorphic for NFKBIA in 3 loci (−519, −826, and −881) or who smoked were at 4.67- to 5.91-fold risk (p<0.05) of developing oral cancer, compared with people with the WT gene who did not smoke." (PMID 22509384, 2012).
type 2 diabetes (5 papers, 2011 to 2023). "In fact, a study discovered that a common NFKBIA variation may change the gene’s expression and is linked to lower estimated glomerular filtration rate (eGFR) at the population level, which may raise the risk of developing type 2 diabetes and impaired renal function." (PMID 36670847, 2023). "TNF, NFkB complex, NFkBIA, NFkB1 and RELA were also involved in type 2 diabetes signaling." (PMID 37047308, 2023).
Crohn disease (4 papers, 2011 to 2025). A gastrointestinal disorder characterized by chronic inflammation involving all layers of the intestinal wall, noncaseating granulomas affecting the intestinal wall and regional lymph nodes, and transmural fibrosis. "For example, TLR7, NFKBIA, NFKBIZ, NFKB2, and TNFRSF19 have been shown to be upregulated in epithelial cells and macrophages during infection with AIEC strains isolated from Crohn’s disease patients." (PMID 40572318, 2025).
gout (4 papers, 2019 to 2024). A condition characterized by painful swelling of the joints, which is caused by deposition of urate crystals. "The core targets of plantain for treating gout are MAPK1, RELA, TNF, NFKBIA, and IFNG, and the key pathways are pathways in cancer, hypoxia-inducible factor-1 (HIF-1) signaling pathway, interleukin (IL)-17 signaling pathway, Chagas disease (American trypanosomiasis), and relaxin signaling pathway." (PMID 33149752, 2020).
inflammatory bowel disease (4 papers, 2014 to 2022). A spectrum of small and large bowel inflammatory diseases of unknown etiology. "Furthermore, polymorphisms in genes encoding TLR2 and NF-κB signaling proteins (NFKB1 and NFKBIA) are associated with risk of inflammatory bowel disease (IBD)." (PMID 27563173, 2016).
influenza (4 papers, 2014 to 2024). An acute viral infection of the respiratory tract, occurring in isolated cases, in epidemics, or in pandemics; it is caused by serologically different strains of viruses (influenzaviruses) designated A, B, and C, has a 3-day incubation period, and usually lasts for 3 to 10 days. "Our results also suggest that, by inhibiting overexpression of the NF-kB1 and NFKBia, the ORNs-d-M can impair influenza-induced overexpression of the cytokines, chemokines, ISGs, and pro-oxidation genes and inhibit influenza virus replication dependent on an active NF-kB signaling pathway." (PMID 30037133, 2018).
pneumonia (4 papers, 2013 to 2026). An acute, acute and chronic, or chronic inflammation focally or diffusely affecting the lung parenchyma, caused by an infection in one or both of the lungs (by bacteria, viruses, fungi, or mycoplasma.). "Our computational-experimental pipeline prioritizes four biomarkers (NAMPT, NFKBIA, SLC40A1, PRKCQ) that stratify pneumonia risk and predict targeted drugs for therapeutic repurposing." (PMID 41557688, 2026). "Transcriptional profiling confirmed marked dysregulation of all four model genes (NAMPT, NFKBIA, SLC40A1, PRKCQ) in pneumonia cases versus controls (p < 0.001)." (PMID 41557688, 2026).
prostate tumor (4 papers, 2005 to 2017). "Compared to the primary prostate tumors, mRNA level of NFKBIA, DUSP6, PLCB3, and SMAD4 are lower in metastatic prostate tumors, while mRNA level of RELA and SNAI1 exhibit opposite trend." (PMID 27191743, 2016). "On the other hand, mRNA levels of ROR2, NFKBIA, DUSP6, PLCB3, and SMAD4 are lower in metastatic prostate tumors as compared to primary prostate tumors." (PMID 27191743, 2016).
cholangiocarcinoma (3 papers, 2018 to 2025). A carcinoma that arises from the intrahepatic biliary tree (intrahepatic cholangiocarcinoma) or from the junction, or adjacent to the junction, of the right and left hepatic ducts (hilar cholangiocarcinoma). "RiskScore of cholangiocarcinoma patients with 10 genes calculated followed the formula: The RiskScore=0.429*VEGFC -0.434*NFKBIA-0.884*NLRX1+0.54*AKT1+0.629*CSRP1+0.406*EPO+0.833*IL31RA+1.023*LEP+0.341*MUC4+0.363*SEMA4B." (PMID 36817485, 2023).
chronic myeloid leukemia (3 papers, 2023 to 2024). "Previous evidences illustrate that RPL32 plays an important role in the SF3B1 mutation for chronic myeloid leukemia (CML) disease progression, CD52 helps identify molecular signature of CML and NFKBIA plays a strategic role in CML molecular response." (PMID 38096269, 2023).
head and neck cancer (3 papers, 2016 to 2022). A primary or metastatic malignant neoplasm affecting the head and neck. "The role of the NFKB1 gene rs28362491 polymorphism and NFKBIA gene rs2233406 polymorphism in the development of head and neck cancer (HNC) remains controversial." (PMID 31612070, 2019).
Hepatitis B (3 papers, 2020 to 2025). "There are 31 intersection targets for hyperuricemia, the main targets are RELA, MAPK1, NFKBIA, CASP3, CASP8, and TNF, and the main pathways include pathways in cancer, apoptosis, hepatitis B, IL-17 signaling pathway, and toxoplasmosis." (PMID 33149752, 2020). "The core targets of plantain for hyperuricemia are RELA, MAPK1, NFKBIA, CASP3, CASP8, and TNF, and the main pathways are pathways in cancer, apoptosis, hepatitis B, IL-17 signaling pathway, and toxoplasmosis." (PMID 33149752, 2020).
lung diseases (3 papers, 2014 to 2025). "Genetic variation in the promoter region in NFKBIA is associated with differential susceptibility to pediatric lung disease." (PMID 26477820, 2015). "They investigated the functional and clinical impact of human genetic variants in the promoter of NFKBIA, which encodes IκBα, the main negative regulator of NF-κB, highlighting how NFKBIA/IκBα is a central hub in the transcriptional responses of the main childhood lung diseases." (PMID 40559430, 2025).
nephritis (3 papers, 2014 to 2025). Inflammation of renal tissue. "Likewise, similar results were obtained when comparing the haplotype frequencies of NFKB1 and NFKBIA between IgAV patients with and without nephritis." (PMID 41208975, 2025).
sarcopenia (3 papers, 2024 to 2025). Progressive decline in muscle mass due to aging which results in decreased functional capacity of muscles. "Specifically, in the sarcopenia dataset, the CEBPB showed the best diagnostic efficiency for differentiating sarcopenia, while BTG2, CDKN1A, CEBPB, DDIT4, and NFKBIA showed the best-differentiating capability in the OA dataset." (PMID 38962732, 2024). "Correspondingly, the sarcopenia model showed marked differential expressions of BCL6, DDIT4, FLNA, FOXO1, NFKBIA, PGK1, and STAT3." (PMID 41282482, 2025). "In the sarcopenia dataset, BTG2 (AUC = 0.867), CDKN1A (AUC = 0.892), CEBPB (AUC = 0.942), DDIT4 (AUC = 0.792), FOXO3 (AUC = 0.900), NFKBIA (AUC = 0.892), ZBTB16 (AUC = 0.808) and ZFP36 (AUC = 0.775) demonstrated better diagnostic efficacy in distinguishing sarcopenia patients from healthy controls." (PMID 38962732, 2024). "The results showed a strong positive correlation (p < 0.01) between NFKBIA and effector.Memory.CD4.T.cell and memory.B.cell, while ZFP36 had a strong negative correlation with both eosinophils and type 2.T.helper.cell cells (p < 0.01) in the sarcopenia datasets." (PMID 38962732, 2024).
triple-negative breast carcinoma (3 papers, 2023 to 2025). An invasive breast carcinoma which is negative for expression of estrogen receptor (ER), progesterone receptor (PR), and human epidermal growth factor receptor 2 (HER2). "These are interesting findings, since other authors have shown that NFIL3 increased tumor progression of triple-negative breast cancer type by suppressing NFKB inhibitor alpha (NFKBIA) transcription." (PMID 39765744, 2024).
vitamin D deficiency (3 papers, 2018 to 2023). A nutritional condition produced by a deficiency of VITAMIN D in the diet, insufficient production of vitamin D in the skin, inadequate absorption of vitamin D from the diet, or abnormal conversion of vitamin D to its bioactive metabolites. "Airway inflammation is also found in case of antenatal vitamin D deficiency, demonstrated by elevated neutrophil and decreased lymphocyte counts in bronchoalveolar lavage, as well as by decreased expression of IkBa through NFKBIA, and by other indicators of postnatal airway inflammation." (PMID 32628705, 2020).
ZIKV infection (3 papers, 2022 to 2023). "In addition, proinflammatory gene transcription induced after RIG-I activation such as IL6 and NFKBIA is independent of DNA-PKcs in A549 cells upon ZIKV infection, but dependent in RPE cells lacking DNA-PKcs." (PMID 36311766, 2022).
astrocytoma (2 papers, 2014 to 2016). "Interestingly, grade III astrocytomas, the most aggressive type of LGG, showed the highest frequency of NFKBIA deletion (16.84%)." (PMID 27052952, 2016).
celiac disease (2 papers, 2012 to 2019). An autoimmune genetic disorder with an unknown pattern of inheritance that primarily affects the digestive tract. "In our analysis we focused on NFKBIA gene, as well as on RELA and TNFAIP3 genes that, similarly to NFKBIA, have been associated with susceptibility to celiac disease." (PMID 31049595, 2019).
cylindroma (2 papers, 2021 to 2023). "In addition, CYLD-wildtype HNSCC with cylindroma-like histology showed a higher frequency of NFKBIA truncating alterations (12% [4/34] vs. 1% [4/425], p = 0.0014)." (PMID 32892208, 2021).
E. coli infection (2 papers, 2017 to 2025). "Such factors having exclusively been induced by the E. coli infection included several TNFα induced proteins (TNFAIP230; TNFAIP331, also known as ubiquitin-editing enzyme A20; TNFAIP632) the suppressors of cytokine signaling SOCS1, SOCS333 and the NF-κB inhibitors NFKBIA, NFKBID, NFKBIE34." (PMID 28684793, 2017).
Fever (2 papers, 2022 to 2024). Body temperature elevated above the normal range. "Low RMSD, RMSF, Rg, and SASA values as well as high intermolecular interactions indicated that GABBR2–saikosaponin C, GABBR2–baicalin, NFKBIA–glycyrrhizic acid, and PTGS2–lobetyolin complexes were quite stable, highlighting their potential as promising candidates for fever treatment." (PMID 38675434, 2024).